SOAT1 (sterol O-acyltransferase 1)
Diseases named in the same sentence as SOAT1 in open-access papers (continued):
Sharing a sentence is not in itself a finding about the gene and the disease.
cancer (continued). "Second, despite that SOAT1 expression was demonstrated to relate to immune and clinical survival in pan-cancer, we are uncertain whether SOAT1 affects clinical survival through an immune pathway." (PMID 37304239, 2023). "SOAT1 can play an essential role in cancer cell proliferation, migration, invasion and metastasis." (PMID 37409263, 2023). "The Estimation of STromal and Immune cells in MAlignant Tumor tissues using Expression data (ESTIMATE) algorithm was then used to calculate the stromal and immune cell scores in pan-cancer, and the correlation between the scores and SOAT1 expression levels was analyzed." (PMID 37304239, 2023). "In this study, we showed that SOAT1 expression is greatly increased in 21 types of cancer." (PMID 37304239, 2023). "The elucidation of the SOAT1 protein crystal structure provides an opportunity to develop a more potent and safer SOAT1 inhibitor with specific binding and high absorptivity, potentially paving the way for the next generation of SOAT1-targeted therapy in cancer." (PMID 37409263, 2023). "In addition, enhanced SOAT1 was significantly correlated with immune checkpoint molecules in various cancers." (PMID 37304239, 2023). "Cell lipid content and quality have recently been suggested to be highly relevant for shaping cancer cell phenotype, and Sterol O-Acyl Transferase 1 (SOAT1), a key enzyme for cholesterol esterification, has been established as an independent predictor of death and recurrence in ACC patients." (PMID 36952130, 2023). "Previous studies on the role of SOAT1 in tumors were restricted to specific types of cancer." (PMID 37304239, 2023). "A pan-cancer analysis was performed to compare the mRNA level of SOAT1 between tumor and corresponding normal tissues in the integrated datasets (combined TCGA with GTEx databases), which revealed that SOAT1 was upregulated in 22/33 tumor types and downregulated in 3 tumor types." (PMID 35646697, 2022). "In recent years, SOAT1 has started to gain significant consideration in the cancer field as accumulating evidence suggests that SOAT1 is a novel and promising drug target in many cancer types." (PMID 36009491, 2022). "Therefore, it is indispensable to explore the oncogenic signaling pathways affected by SOAT1 inhibition and approaches to sensitize cells to SOAT1-targeted therapy in cancer." (PMID 33637695, 2021). "Following these previous findings, SOAT1 is a promising therapeutic target for cancer management." (PMID 33637695, 2021). "SOAT1 is frequently upregulated in multiple cancers, including GBM, HCC and PCa." (PMID 34790132, 2021). "Taken together, these results strongly suggest that the elevated expression of SOAT1 may be a general feature of diverse cancers, and that this protein might be widely used as a prognosis biomarker and therapeutic target for multiple tumors." (PMID 31963898, 2020). "Finally, the latest developments that target SOAT1 for cancer treatment are summarized." (PMID 37409263, 2023). "Could other proteins in addition to DGAT1 and SOAT1 serve as druggable targets for cancer therapy?" (PMID 36009491, 2022). "Perilipin 2 (PLIN2) and sterol O-acyltransferase 1 (SOAT1) are two proteins used to identify sebaceous glands in tissue sections while keratin 14 (KRT14) is useful for outlining the gland when investigating its involvement in cancer or for structural abnormalities." (PMID 30372477, 2018). "This study underscores the critical role of tumor-intrinsic cholesterol metabolism in cancer prognosis, highlighting the prognostic significance of de novo cholesterol synthesis markers such as SREBP-1, SQLE, and SOAT1." (PMID 40707931, 2025). "In contrast, SOAT1 (uncomfortable attitudes from others) (0.540), DISC1 (avoids cancer-related activities) (0.584), and CONC1 (downplays condition) (0.597) showed relatively lower, but still acceptable, factor loadings." (PMID 41346501, 2025).
cancer (continued). "Taken together, these findings suggest that as the downstream of SOAT1, NLRP3 inflammasome activation positively impacted cancer‐related lymphangiogenesis in OSCC." (PMID 40135589, 2025). "We firstly evaluated the DNA alterations of SOAT1 and SOAT2 in the Cancer Genome Atlas (TCGA) pan-cancers via cBioPortal." (PMID 34052835, 2021). "Genetically silencing SOAT1/ACAT1 or blocking its activity using the inhibitors K604, ATR-101 or avasimibe effectively suppresses tumor growth in several cancer xenograft models." (PMID 29784041, 2018). "In conclusion, SOAT1 could promote OSCC malignancy and regulate the activation of NLRP3 inflammasome to increase the rate of lymphangiogenesis and cancer metastasis via IL‐1β/IL‐1R‐1 axis in OSCC." (PMID 40135589, 2025). "In addition, some new cholesterol metabolism molecules, such as SOAT1, SQLE and NPC1, have recently become promising drug targets for cancer treatment." (PMID 38817876, 2024). "Nevertheless, the predictive value of SOAT1 regarding immune responses in cancer is not fully understood." (PMID 37304239, 2023). "To date, clinical trials have not extensively evaluated the efficacy of SOAT1 inhibitors for cancer treatment, with the exception of nevanimibe in a phase I study." (PMID 37409263, 2023). "Thus, investigating the relationships between SOAT1 expression level and TMB and MBI in different types of cancer is warranted." (PMID 37304239, 2023). "In the present study, we found that targeting SOAT1 could activate the PCP-YAP axis in a cholesterol-dependent manner, whereas nystatin sensitized cancer cells to avasimibe via cholesterol sequestration." (PMID 33637695, 2021). "Based on our data mining, although single SOAT1 inhibition indeed reduced cell proliferation in HCC, the anti-cancer effect could be counteracted by provoking the activity of the FAO pathway." (PMID 34052835, 2021). "On the other hand, our results also suggest that the impact of SOAT1 on HCC might be limited, calling for continuing search of other HCC host proteins involved in this multigenic heterogenous cancer." (PMID 34039309, 2021). "Strong SOAT1 expression was found in 42 out of 112 carcinomas (37.5%), and a weak or absent SOAT1 protein expression was observed in the remaining cases." (PMID 31963898, 2020). "Third, from our in silico gene deletion analysis, we identified Sterol O-Acyltransferase 1 (SOAT1), methylmalonyl-CoA mutase (MUT), and isozymes of succinate dehydrogenase (SDHA, SDHB, SDHC, and SDHD) as having a significant effect (p-value < 0.05) in cancer as compared to normal samples." (PMID 33396819, 2020). "To investigate whether SREBP1 and SREBP2 involved in SOAT1-mediated lymphangiogenesis and VEGFC production, we pharmacologically inhibited SREBP1 and SREBP2 by fatostatin, which displays antitumor activity in cancers by downregulating SREBP- mediated metabolic pathways." (PMID 34790132, 2021).
tumor (1,740 papers, 2002 to 2026). "In gastric cancer, SOAT1 was highly expressed in cancerous tissues, associating with advanced tumor stage, lymph node metastasis, and poor prognosis." (PMID 40135589, 2025). "We then analyzed the potential associations between the expression of SOAT1 and tumor-infiltrating immune cells or related immune markers." (PMID 37304239, 2023). "The deficient of SOAT1 or SOAT1 inhibition would disturb cholesterol homeostasis, and then inhibits the activities of SREBPs and eventually suppresses tumor development." (PMID 37409263, 2023). "Tumor cells exhibit metabolic abnormalities to meet the elevated energy and biosynthetic demands associated with rapid tumor growth, and thus SOAT1 has become an essential target of metabolic therapy for tumor treatment." (PMID 35646697, 2022). "The results of our analysis underline the differences between both tumor subtypes and raise doubt regarding a potential therapy success by suppression of SOAT1 in HGA." (PMID 35409086, 2022). "SOAT1 was associated with advanced tumor stage and lymph node metastasis, leading to the poor prognosis of GC." (PMID 35785165, 2022). "Of note, SOAT1 deficiency in CD8+ T cells augments their tumor-killing ability via increasing the cholesterol content on the plasma membrane and subsequently promoting T-cell receptor (TCR) clustering and immunological synapse formation in CD8+ T cells." (PMID 34820325, 2021). "We also found that inhibition of SOAT1 effectively reduced tumor-associated lymphangiogenesis and the migratory ability of HLECs." (PMID 34790132, 2021). "In this research, we identified a rate-limiting enzyme, sterol O-acyltransferase 1 (SOAT1), was highly expressed in cancerous tissues, which was associated with advanced tumor stage and lymph node metastasis, leading to the poor prognosis of GC." (PMID 34790132, 2021). "The high SOAT1-expression in tumor-associated macrophages could be the basis for a therapeutic attempt with mitotane, in GBM patients with no further therapeutic options." (PMID 35409086, 2022). "The results indicated that SOAT1 expression levels in OSCC tumor tissues (n = 520) were significantly higher than those in the control group (n = 44, p < 0.001)." (PMID 40135589, 2025). "The results showed that all included OSCC patients (n = 51) displayed positive SOAT1 expression in their tumor tissues." (PMID 40135589, 2025). "The knockdown of SOAT1 in Cal‐27 cells significantly impacted the gene enrichment of several lipid metabolism pathways, indicating substantial alterations in lipid metabolism within tumor cells following SOAT1 knockdown." (PMID 40135589, 2025). "By controlling cholesterol homeostasis in tumor cells, inhibiting or knocking down SOAT1 can effectively suppress various types of cancer." (PMID 40122853, 2025). "This explains why SQLE and SOAT1 overexpression consistently predicts poor prognosis, they represent metabolic escape pathways that enable sustained tumor growth despite HMGCR constraints." (PMID 40707931, 2025). "Targeting the cholesterol metabolism of tumors through sterol O-acyltransferase 1 (SOAT1)-targeted drugs alters tumor cholesterol metabolism and increases CD8+ T lymphocytes and neutrophils, thus preventing HCC development." (PMID 40122853, 2025). "The results found an increased SOAT1 expression in tumor tissues compared to that in normal epithelial tissues (p = 0.0079)." (PMID 40135589, 2025). "To confirm database results, we evaluated the expression of LYVE‐1 in clinical paraffin embedded samples, revealing that patients with higher SOAT1 expression exhibited higher expression of LYVE‐1 in tumor tissues." (PMID 40135589, 2025).
tumor (continued). "In our study, we observed a higher density of lymphatic vessels in tumor tissues with higher SOAT1 expression, showing the positive correlation between SOAT1 and lymphangiogenesis." (PMID 40135589, 2025). "Increasing evidence indicates that the suppression of SOAT1 blocked tumor growth, such as glioblastoma, pancreatic cancer, colon cancer, and gastric cancer." (PMID 38724499, 2024). "In tumor sphere formation experiments, our results suggested that in SOAT1-overexpressing cells, the ability to form tumor spheres was significantly increased compared to the control." (PMID 38993570, 2024). "The xenograft tumor and lung metastasis model in vivo revealed that SOAT1 accelerated tumor growth and metastasis." (PMID 38724499, 2024). "Compared with the mice in Control group, SOAT1 promoted the tumor growth, and the opposite results were obtained after silencing SOAT1 expression." (PMID 38724499, 2024). "Nootkatone administration inhibited tumor growth and eliminated the stimulative roles of SOAT1 on tumor growth." (PMID 38724499, 2024). "By CCK-8, tumor sphere formation, colony formation, and transwell assays, we noticed that the knockdown of SOAT1 dramatically inhibited the proliferation, migration, and invasion abilities of OSCC cells." (PMID 38993570, 2024). "In depth, the results showed that tumor related and lipid metabolism-related genes such as cholesterol metabolism genes were increased, including SOAT1." (PMID 38724499, 2024). "Avasimibe, a well-studied inhibitor of cholesterol esterification, has been found to effectively suppress tumor cell proliferation by targeting ACAT1 (SOAT1) to inhibit CE production." (PMID 38617549, 2024). "Studies have showed that high SOAT1 expression elevated lipid availability, which can promote tumor aggressiveness." (PMID 37409263, 2023). "A gene set enrichment analysis (GSEA) revealed that the expression of SOAT1 correlated with the tumor microenvironment, adaptive immune response, interferon signaling, and cytokine signaling." (PMID 37304239, 2023). "Clinical trials targeting cholesterol metabolism, including statins and SOAT1 inhibitors, exhibit potential anti-tumor effects, and combination therapies enhance efficacy." (PMID 37958351, 2023). "Our findings suggest that interfering with SOAT1 activity has the potential to disrupt tumor proliferation and enhance the therapeutic sensitivity induced by ferroptosis." (PMID 37980334, 2023). "Nevertheless, both the mechanism by which SOAT1 promotes tumor growth and immune escape need to be further studied." (PMID 37409263, 2023). "In HCC, the protein expression of SOAT1 was significantly increased in the tumor compared with adjacent tissue." (PMID 37409263, 2023). "A recent study noted that SOAT1 expression was positively correlated with various tumor infiltrating immune cells in glioma." (PMID 37409263, 2023). "Results revealed that depletion of Soat1 significantly repressed both volumes and sizes of tumors, as well as tumor multiplicities for both colon and small intestine tumors in ApcMin/+ mice when compared with WT littermates on an ApcMin/+ mouse background." (PMID 34914638, 2022). "SOAT1 is highly expressed in cancerous tissues and correlated with advanced tumor stage and lymph node metastasis, leading to a poor prognosis of GC." (PMID 35785165, 2022). "IHC staining showed that Ki-67, CD31 and SOAT1 levels were significantly positively correlative with circLDLR contents in xenograft tumor tissues." (PMID 35821230, 2022). "In all tumor samples, the proportion of SOAT1-positive microglia/macrophages was higher than that of tumor cells." (PMID 35409086, 2022).
tumor (continued). "Immunohistochemical staining of SOAT1 in tumors after administration of the compounds showed that SOAT1 protein in the tumor tissues of mice was significantly lower than that of the control group." (PMID 35941608, 2022). "Recognizing the potential of SOAT1 protein in tumor therapy, several international teams have successively reported the precise crystal structure of SOAT1, which provides a new opportunity for target protein-based drug development." (PMID 35941608, 2022). "In this study, we applied proteomics and integrated metabolomics analysis to explore the effects of SOAT1-targeting compounds on the cholesterol metabolism signaling pathways in tumor cells." (PMID 35941608, 2022). "Our group discovered that SOAT1 expression is highly upregulated in tumor tissues from GBM patients, while SOAT2 is undetectable in tumor tissues." (PMID 36009491, 2022). "Knockdown or inhibition of SOAT1 can inhibit a variety of tumors by regulating cholesterol homeostasis in tumor cells, and the immune state of the tumor microenvironment." (PMID 35941608, 2022). "In our panel of 27 GBM and 3 HGA, CNS WHO grade 4, only a small proportion of the tumor cells displayed SOAT1-immunoreactivity." (PMID 35409086, 2022). "In particular, nilotinib displayed a high affinity for SOAT1 protein and significantly inhibited tumor activity both in vitro and in vivo." (PMID 35941608, 2022). "The expression level of SOAT1 was negatively correlated with purity of tumor in GBM and LGG (r=-0.27, P=1.36e-03, r=-0.03, P=-5.10e-01)." (PMID 35646697, 2022). "The same study found that in a patient-derived tumor xenograft mouse model suppression of SOAT1 reduced tumor size." (PMID 34039309, 2021). "In the immunohistochemistry experiment, we found that the protein expression of SOAT1 was significantly increased in the tumor compared with adjacent tissue (P < 0.001)." (PMID 34039309, 2021). "We conducted paired Wilcoxon signed-rank test for IHC score differences and found SOAT1 has a markedly higher expression level in tumor tissues compared to paired non-tumor tissues (P < 0.001, paired Wilcoxon singed-rank test)." (PMID 34039309, 2021). "Inhibition of SOAT1 using avasimibe reduced serum CE level and tumor weight as well as Ki-67 positive cell population." (PMID 34201030, 2021). "SOAT1 depletion in mesothelin-directed chimeric antigen receptor T cells (CART) can strengthen their anti-tumor response against pancreatic carcinoma in vitro or in vivo." (PMID 34820325, 2021). "Sterol O-acyltransferase 1 (SOAT1) was introduced as the specific signature of S-III which its inhibition by avasimibe significantly reduced tumor size." (PMID 33198323, 2020). "In vivo experiments demonstrated that SOAT1 could help tumor growth and promote OSCC metastasis to cervical lymph nodes." (PMID 40135589, 2025). "Additional research evidence also supports the regulatory role of SOAT1 in tumor metastasis." (PMID 40135589, 2025). "Moreover, we conducted migration and invasion assays using transwell chambers to reinforce the impact of SOAT1 on tumor invasiveness in Cal‐27 and HSC‐3 cells." (PMID 40135589, 2025). "Inhibiting the activity of SOAT1 can block the proliferation and metastasis of tumor cells 11-13." (PMID 38993570, 2024). "In addition, nootkatone treatment significantly inhibited the xenograft tumor growth and pulmonary metastasis via targeting SOAT1." (PMID 38724499, 2024). "Taken together, we have clarified an important mechanism by which SOAT1 promotes OSCC tumor growth." (PMID 38993570, 2024). "Thus, SOAT1 is a potential marker for predicting prognosis and a promising tumor immunotherapy target." (PMID 37304239, 2023). "Avasimibe, a sterol O-acyltransferase 1 inhibitor, has also been utilized to prevent cholesterol esterification, which raises cholesterol levels and impairs T-cell effector function and proliferation, improving the anti-tumor impact." (PMID 36677919, 2023).